RNU4-43P (RNA, U4 small nuclear 43, pseudogene)
Gene: Small nuclear RNA gene on chromosome 5 (26,012,889 to 26,013,025, forward strand). Ensembl gene ENSG00000222560.
Homologues: Orthologues: chimpanzee U4 (96% identical), macaque U4 (91% identical). Paralogues in human: RNU4-46P (75% identical), RNU4-52P (74% identical), RNU4-66P (73% identical), RNU4-51P (72% identical), RNU4-24P (67% identical), RNU4-10P (66% identical), RNU4-32P (65% identical), RNU4-17P (64% identical), RNU4-49P (64% identical), RNU4-50P (64% identical), RNU4-81P (64% identical), RNU4-90P (63% identical), and 80 more.